KCNC2 (potassium voltage-gated channel subfamily C member 2)
Description:
Voltage-gated potassium channel that mediates transmembrane potassium transport in excitable membranes, primarily in the brain. Contributes to the regulation of the fast action potential repolarization and in sustained high-frequency firing in neurons of the central nervous system. Homotetramer channels mediate delayed-rectifier voltage-dependent potassium currents that activate rapidly at high-threshold voltages and inactivate slowly. Forms tetrameric channels through which potassium ions pass in accordance with their electrochemical gradient. The channel alternates between opened and closed conformations in response to the voltage difference across the membrane (Probable). Can form functional homotetrameric and heterotetrameric channels that contain variable proportions of KCNC1, and possibly other family members as well; channel properties depend on the type of alpha subunits that are part of the channel. Channel properties may be modulated either by the association with ancillary subunits, such as KCNE1, KCNE2 or KCNE3 or indirectly by nitric oxide (NO) through a cGMP- and PKG-mediated signaling cascade, slowing channel activation and deactivation of delayed rectifier potassium channels (By similarity). Contributes to fire sustained trains of very brief action potentials at high frequency in retinal ganglion cells, thalamocortical and suprachiasmatic nucleus (SCN) neurons and in hippocampal and neocortical interneurons. Sustained maximal action potential firing frequency in inhibitory hippocampal interneurons is negatively modulated by histamine H2 receptor activation in a cAMP- and protein kinase (PKA) phosphorylation-dependent manner. Plays a role in maintaining the fidelity of synaptic transmission in neocortical GABAergic interneurons by generating action potential (AP) repolarization at nerve terminals, thus reducing spike-evoked calcium influx and GABA neurotransmitter release. Required for long-range synchronization of gamma oscillations over distance in the neocortex. Contributes to the modulation of the circadian rhythm of spontaneous action potential firing in suprachiasmatic nucleus (SCN) neurons in a light-dependent manner (By similarity).
Synonyms: Kv3.2; DEE103
Tractability: Small molecule: an approved drug acts on it; it belongs to a druggable protein family. Antibody: its Gene Ontology location is reachable by antibodies, with high confidence; UniProt places it where antibodies can reach, with medium confidence; UniProt predicts a signal peptide or a membrane-spanning region.
Target class: Potassium channels; Ion channel; Voltage-gated ion channel; Voltage-gated potassium channel
Gene: Protein-coding gene on chromosome 12 (75,040,077 to 75,209,839, reverse strand). Ensembl gene ENSG00000166006.
Subcellular location: Cell membrane; Membrane; Perikaryon; Cell projection, axon; Cell projection, dendrite; Postsynaptic cell membrane; Presynaptic cell membrane; Synapse, synaptosome; Synapse; Apical cell membrane; Basolateral cell membrane
Pathways (Reactome):
Metabolism: Glucagon-like Peptide-1 (GLP1) regulates insulin secretion
Neuronal System: Voltage gated Potassium channels
Gene Ontology:
Molecular function: voltage-gated potassium channel activity; delayed rectifier potassium channel activity; gated channel activity; monoatomic ion channel activity; transmembrane transporter binding; voltage-gated monoatomic ion channel activity involved in regulation of presynaptic membrane potential
Biological process: potassium ion transport; action potential; cellular response to nitric oxide; membrane hyperpolarization; nitric oxide-cGMP-mediated signaling; potassium ion transmembrane transport; protein heterooligomerization; protein homooligomerization; regulation of action potential firing rate; cellular response to ammonium ion; cellular response to toxic substance; globus pallidus development; monoatomic ion transmembrane transport; monoatomic ion transport; optic nerve development; positive regulation of potassium ion transmembrane transport; regulation of presynaptic membrane potential; response to amine; response to ethanol; response to kainic acid; response to light intensity; response to magnesium ion; response to nerve growth factor; response to toxic substance; transmembrane transport
Cellular component: apical plasma membrane; axon; axon terminus; basolateral plasma membrane; cell body; dendrite; dendrite membrane; membrane; neuronal cell body membrane; perikaryon; plasma membrane; postsynaptic membrane; presynaptic membrane; synapse; voltage-gated potassium channel complex; axolemma; GABA-ergic synapse; neuronal cell body; terminal bouton; vesicle
Genetic constraint (gnomAD): Loss-of-function variants: 19 observed, 41.86 expected, observed/expected ratio (o/e) 0.45, 90% interval 0.32 to 0.67. The upper end of that interval is the gene's LOEUF score, 0.67, which puts it in group 2 of 6, group 1 being the genes least tolerant of losing a copy. Missense variants: 583 observed, 836.54 expected, observed/expected ratio (o/e) 0.7, 90% interval 0.65 to 0.75. Synonymous variants: 390 observed, 344.82 expected, observed/expected ratio (o/e) 1.13, 90% interval 1.04 to 1.23.
Gene-disease validity (ClinGen):
ClinGen rates the evidence that KCNC2 causes each of these diseases.
genetic developmental and epileptic encephalopathy (autosomal dominant): Definitive. A complex neurodevelopmental disorder characterized by a range of developmental delays and epileptic encephalopathy phenotypes.
Homologues: Orthologues: chimpanzee KCNC2 (100% identical), macaque KCNC2 (100% identical), pig KCNC2 (98% identical), mouse Kcnc2 (97% identical), rabbit KCNC2 (97% identical), dog KCNC2 (93% identical), rat Kcnc2 (92% identical), tropical clawed frog kcnc2 (80% identical), guinea pig KCNC2 (64% identical), zebrafish kcnc4 (57% identical), zebrafish kcnc2 (45% identical), zebrafish si:ch73-334d15.4 (28% identical). Paralogues in human: KCNC4 (65% identical), KCNC1 (62% identical), KCNC3 (61% identical), KCNB2 (30% identical), KCNA3 (29% identical), KCNA4 (29% identical), KCNA2 (28% identical), KCNA1 (28% identical), KCNA6 (28% identical), KCNA5 (28% identical), KCNA7 (27% identical), and 19 more.
Diseases named in the same sentence as KCNC2 in open-access papers:
KCNC2 is named in the same sentence as 33 diseases in open-access papers, as found by Europe PMC text mining. Sharing a sentence is not in itself a finding about the gene and the disease. The quoted sentences say what the papers report.
epilepsy (9 papers, 2017 to 2025). A brain disorder characterized by episodes of abnormally increased neuronal discharge resulting in transient episodes of sensory or motor neurological dysfunction, or psychic dysfunction. "Mutations in KCNC2 have been identified as causative factors for epilepsy and modifying factors for an array of neuropsychiatric disorders, including SZ." (PMID 40806641, 2025). "Genetic variants in KCNC2 were linked to severe neurodevelopmental phenotypes, including epilepsy, speech disturbance, depression, and hyperactivity, though more research is required to show a direct link with SZ." (PMID 40806641, 2025). "Although valproate was reported to result in seizure freedom for some KCNC2 patients, many patients with KCNC2 variants had drug resistant epilepsy." (PMID 39881864, 2024). "Patients with KCNC2 variants have similar types of epilepsy with respect to age of onset and severity." (PMID 39881864, 2024). "Gain-of-function (GOF) de novo pathogenic variants in KCNC1 and KCNC2, encoding Kv3.1 and Kv3.2 respectively, cause several types of epilepsy including developmental and epileptic encephalopathy (DEE)." (PMID 39881864, 2024). "In this work, we have reported the functional consequences of four variants in the KCNC2 gene, which has recently been reported as a novel epilepsy gene." (PMID 37360341, 2023). "This in vivo evidence suggests that human KCNC2 loci are linked to epilepsies." (PMID 36090251, 2022). "The data presented here support that KCNC2 variants with uncertain significance may also be causative for various forms of epilepsy, as they show changes in the current amplitude and activation and deactivation kinetics of the channel, depending on the variant." (PMID 37360341, 2023). "Recently, de novo variants in KCNC2, coding for the potassium channel subunit KV3.2, have been described as causative for various forms of epilepsy including genetic generalized epilepsy (GGE) and developmental and epileptic encephalopathy (DEE)." (PMID 37360341, 2023). "Recently, we described variants in the KCNC2 gene, encoding the potassium channel subunit KV3.2, as causative for several forms of epilepsy, including genetic generalized epilepsy (GGE) and developmental and epileptic encephalopathy (DEE)." (PMID 37360341, 2023). "KCNC2 has been independently suggested to be a new candidate epilepsy gene." (PMID 38992748, 2024). "We could demonstrate that also variants of uncertain significance in KCNC2 classified by the ACMG criteria can have a significant effect on the channel function and therefore be associated to different epilepsy phenotypes." (PMID 37360341, 2023). "In this work, we mainly wanted to test if variants in KCNC2 that were defined as variants of uncertain significance (VUS) according to the ACMG criteria, also show a functional effect and can be associated to the epilepsy phenotype." (PMID 37360341, 2023). "Another undeniable advantage of using WES is the possibility of identifying new possible candidate genes; the present study led to the identification of three genes never before related to epilepsy, namely, KCNC2, STXBP6 and DHRS9." (PMID 38256219, 2024).
developmental and epileptic encephalopathy (4 papers, 2023 to 2025). An epilepsy associated with developmental impairment that may be due to either the underlying etiology or the superimposed epileptic activity, or both. "Due to our first KCNC2 signaling in DEEs and subsequent reports from the international scientific community, today, the KCNC2 gene (OMIM# 176256) is considered responsible for Developmental and Epileptic Encephalopathy 103 (DEE103; 619913)." (PMID 38256219, 2024).
Epileptic encephalopathy (4 papers, 2022 to 2024). A condition in which epileptiform abnormalities are believed to contribute to the progressive disturbance in cerebral function. "Recently, a novel LOF KCNC2 variant V437A was detected in two siblings diagnosed with autism, epileptic encephalopathy, and mild dysmorphism." (PMID 36090251, 2022). "Multiple Kcnc2 variations have been associated with epileptic encephalopathy." (PMID 38544384, 2024). "Developmental and epileptic encephalopathies (DEEs) have high genetic heterogeneity, and DEE due to the potassium voltage-gated channel subfamily C member 2 (KCNC2) variant remains poorly understood, given the scarcity of related case studies." (PMID 36090251, 2022).
spinocerebellar ataxia (4 papers, 2020 to 2022). "The Kv3 subfamily is closely associated with neurological disorders, such as KCNC 3 (Kv3.3) missense mutations found in spinocerebellar ataxia and the absence of KCNC2 chromosomes in patients with neurodevelopmental retardation and ataxia." (PMID 35299674, 2022).
diabetes (3 papers, 2009 to 2024). "More interestingly, an integrative study identifies KCNC2 as a novel predisposing factor for childhood obesity and the risk of diabetes in the Korean population; Kcnc2 is associated with modified hepatic gluconeogenesis and increased ER stress in obesity‐mediated diabetic risk." (PMID 38544384, 2024). "Among the genes that were significantly up-regulated in diabetes were Retnla, Gjb2, Itga, Slit and Dusp6, and among the genes that were down-regulated were Krueppel-like factor 8, IGFBP, Ngfg, Foxa3, Kcnc2 and Dlp8." (PMID 19649297, 2009).
autism (2 papers, 2022 to 2025). Persistent deficits in social interaction and communication and interaction as well as a markedly restricted repertoire of activity and interest as well as repetitive patterns of behavior. "A research study of autism identified the same pathogenic de novo variant in a new disease gene (KCNC2) in two affected siblings using non-CLIA research sequencing." (PMID 41523628, 2025).
bipolar disorder (2 papers, 2010 to 2023). A disorder of the brain that causes unusual shifts in mood, energy, activity levels and the ability to carry out day-to-day tasks. "Studies have shown that overexpression of the KCNC2 gene in hippocampal neurons may lead to higher amplitude and faster dynamics of potassium currents, which are linked to neuronal hyperexcitability in patients with bipolar disorder." (PMID 37715240, 2023). "KCNQ5 (potassium voltage-gated channel subfamily KQT member 5) may contribute to episodic disturbances of mood and behavior as well-characterized roles in other ion-channelopathies, and two family members, KCNC2 and KCNQ2, were found to be associated with bipolar disorder." (PMID 20808825, 2010).
Obesity (2 papers, 2016 to 2024). Accumulation of substantial excess body fat. "Using integrated bioinformatics analysis and machine learning methods, we identified two hub genes (Sytl4 and Kcnc2) and developed a nomogram to assess obesity risk in offspring exposure to maternal obesity." (PMID 38544384, 2024). "Here, we identified Kcnc2 as a hub gene for determining obesity risk in offspring with maternal obesity." (PMID 38544384, 2024). "This study identified two candidate hub genes (Sytl4 and Kcnc2), developed a nomogram for diagnosing the obesity‐associated risks in offspring and presented a dysregulated proportion of immune cells in the hypothalamus of offspring due to maternal obesity." (PMID 38544384, 2024). "Two candidate hub genes (Sytl4 and Kcnc2) were identified and a nomogram was developed to predict obesity risk in offspring with maternal obesity." (PMID 38544384, 2024). "Our study systematically identified two candidate hub genes (Sytl4 and Kcnc2) and developed a nomogram for diagnosing the obesity‐associated risks in offspring through various bioinformatics analyses and machine learning algorithms." (PMID 38544384, 2024). "Our study identified a novel KCNC2 gene as a predisposing factor for susceptibility to both childhood- and adult- obesity in the Korean population." (PMID 27623749, 2016). "Further functional studies in cellular and mouse models demonstrated that KCNC2 is associated with anti-obesogenic effects in the regulation of obesity-induced insulin resistance." (PMID 27623749, 2016). "Taken together, these data suggest that reduction of KCNC2 is associated with modified hepatic gluconeogenesis and increased ER stress on obesity-mediated diabetic risk." (PMID 27623749, 2016). "In conclusion, our integrative analyses of genetic variation and epigenetic regulation identified a novel KCNC2 as a predisposing factor in conferring susceptibility to obesity-associated T2D risk in the Korean population." (PMID 27623749, 2016). "Here, through integrated bioinformatics analyses and machine learning methods, we identified two pivotal immune‐associated candidate genes (Sytl4 and Kcnc2) and constructed a nomogram for diagnosing the obesity‐associated risk in the offspring of mothers with obesity." (PMID 38544384, 2024). "The expression and potential function of Kcnc2 in hypothalamus programing and inflammation in obesity remained unknown." (PMID 38544384, 2024).
epilepsy syndrome (1 paper, 2023). A syndrome that has a characteristic cluster of clinical features and/or lectroencephalographic (EEG) findings that reflect underlying epileptic activity. "Here, we describe that also variants of uncertain significance in KCNC2 may also be the underlying genetic etiology for different epilepsy syndromes." (PMID 37360341, 2023).
glioma (1 paper, 2008). A benign or malignant brain and spinal cord tumor that arises from glial cells (astrocytes, oligodendrocytes, ependymal cells). "In total, we confirmed 14 genes with glioma-specific splicing; seven were novel events identified by the exon expression array (A2BP1, BCAS1, CACNA1G, CLTA, KCNC2, SNCB, and TPD52L2)." (PMID 18474104, 2008).
Hypertension (1 paper, 2024). The presence of chronic increased pressure in the systemic arterial system. "DNA microarray analysis performed on a spontaneously hypertensive rat model identified Kcnc2 as a key gene linked to the onset of hypertension." (PMID 38544384, 2024).
Hypsarrhythmia (1 paper, 2022). Hypsarrhythmia is abnormal interictal high amplitude waves and a background of irregular spikes. "Consistent with the literature, we found that focal impaired awareness seizure with an EEG of polymorphic generalized spike and wave complexes and infantile spasms with a typical EEG showing hypsarrhythmia were two traits of seizures attributed to KCNC2 defects." (PMID 36090251, 2022).
Infertility (1 paper, 2023). "In conclusion, we suggest that difficulty falling asleep among women may influence the occurrence of infertility through DNA methylation of the KCNC2 gene." (PMID 37715240, 2023).
prostate carcinoma (1 paper, 2018). A carcinoma that arises from epithelial cells of the prostate gland. "Notably, they included DMRs close to many genes previously implicated in prostate cancer (e.g., NEAT1, MTOR, RHCG, KCNC2, WT1, HOXC12, KMT2B)." (PMID 30318509, 2018).
cancer (1 paper, 2022). A tumor composed of atypical neoplastic, often pleomorphic cells that invade other tissues. "Furthermore, we illustrated the expression of pyroptosis immune regulators across another∼10000 samples and revealed that CNST, GDF10, KCNC2, NAP1L2, NCOA7, and LINC00641 also revealed higher expression in cancer cells." (PMID 35620284, 2022).
KCNC2 also shares sentences with these, for which no sentence is quoted: schizophrenia (4 papers); Alzheimer disease (2); Ataxia (1); channelopathy (1); depression (1); encephalopathies (1); genetic generalized epilepsy (1); gynecological cancers (1); infantile spasms (1); Insulin resistance (1); long-QT syndrome (1); neurological disorders (1); overnutrition (1); Parkinsonism (1); progressive myoclonus epilepsy (1); psychiatric disorder (1); spinocerebellar ataxia type 13 (1); tumor (1).